WDR45 (WD repeat domain 45)
Description:
Component of the autophagy machinery that controls the major intracellular degradation process by which cytoplasmic materials are packaged into autophagosomes and delivered to lysosomes for degradation. Binds phosphatidylinositol 3-phosphate (PtdIns3P). Activated by the STK11/AMPK signaling pathway upon starvation, WDR45 is involved in autophagosome assembly downstream of WIPI2, regulating the size of forming autophagosomes. Together with WIPI1, promotes ATG2 (ATG2A or ATG2B)-mediated lipid transfer by enhancing ATG2-association with phosphatidylinositol 3-monophosphate (PI3P)-containing membranes. Probably recruited to membranes through its PtdIns3P activity.
Synonyms: WIPI-4; WDRX1; WIPI4; JM5; NBIA5; NBIA4
Tractability: PROTAC: ubiquitination databases record sites on it; its protein half-life has been measured.
Gene: Protein-coding gene on chromosome X (49,074,433 to 49,101,203, reverse strand). Ensembl gene ENSG00000196998.
Subcellular location: Preautophagosomal structure; Cytoplasm
Pathways (Reactome):
Autophagy: Macroautophagy
Gene Ontology:
Molecular function: phosphatidylinositol phosphate binding; phosphatidylinositol-3-phosphate binding; protein binding; protein kinase binding; phosphatidylinositol-3,5-bisphosphate binding; protein-macromolecule adaptor activity
Biological process: autophagosome assembly; autophagy; cellular response to starvation; positive regulation of autophagosome assembly; autophagy of mitochondrion; glycophagy; nucleophagy; pexophagy; protein localization to phagophore assembly site
Cellular component: cytoplasm; phagophore assembly site; phagophore assembly site membrane
Gene-disease validity (ClinGen):
ClinGen rates the evidence that WDR45 causes each of these diseases.
X-linked complex neurodevelopmental disorder (X-linked): Definitive. A complex neurodevelopmental disorder that is transmitted via X-linked inheritance, and is characterized by intellectual disability, autism and epilepsy.
Homologues: Orthologues: chimpanzee WDR45 (100% identical), macaque WDR45 (100% identical), pig WDR45 (99% identical), dog WDR45 (98% identical), guinea pig WDR45 (98% identical), rat Wdr45 (98% identical), mouse Wdr45 (98% identical), zebrafish wdr45 (90% identical), rabbit WDR45 (86% identical), tropical clawed frog wdr45 (85% identical), Caenorhabditis elegans epg-6 (32% identical). Paralogues in human: WDR45B (48% identical), WIPI1 (29% identical), WIPI2 (27% identical).
Diseases named in the same sentence as WDR45 in open-access papers:
WDR45 is named in the same sentence as 60 diseases in open-access papers, as found by Europe PMC text mining. Sharing a sentence is not in itself a finding about the gene and the disease. The quoted sentences say what the papers report.
Encephalopathy (9 papers, 2015 to 2022). Encephalopathy is a term that means brain disease, damage, or malfunction. "Consistent with this idea, mutations in the WIPI4 (WDR45) gene cause static encephalopathy of childhood with neurodegeneration in adulthood (SENDA), a human genetic disease involving neurodegeneration." (PMID 32528724, 2020). "It was also previously shown that heterozygotic mutations in Atg18/WDR45/WIPI4 are associated with static encephalopathy of childhood with neurodegeneration in adulthood (SENDA)." (PMID 28737703, 2017). "For example, mutations in the WD repeat domain 45 (WDR45) gene, which functions in formation of the double membrane structures (“phagophores”), were shown to cause static encephalopathy of childhood with neurodegeneration in adulthood (SENDA)." (PMID 31681409, 2019). "WDR45 is a redundant, non-core autophagy gene, one of four mammalian homologs to Atg18, and mutations in WDR45 cause SENDA, static encephalopathy of childhood with neurodegeneration in adulthood." (PMID 26812546, 2016).
Parkinsonism (9 papers, 2017 to 2026). Characteristic neurologic anomaly resulting from degeneration of dopamine-generating cells in the substantia nigra, a region of the midbrain, characterized clinically by shaking, rigidity, slowness of movement and difficulty with walking and gait. "Monogenic disorders in this pathway include WDR45 deficiency with a bi-phasic disorder from developmental and epileptic–dyskinetic encephalopathy to adult dystonia–Parkinsonism." (PMID 37895210, 2023). "WDR45 (WD repeat domain 45) is a protein mutated in neurodegeneration with brain iron accumulation presenting with Parkinsonism." (PMID 28202669, 2017). "Defects in WDR45/WIPI4 cause BPAN, a disorder with a biphasic presentation of early childhood onset seizures and global developmental delay followed by progressive dementia, parkinsonism, and dystonia in adolescence or early adulthood." (PMID 41277110, 2026). "The WD repeat domain 45 (WDR45) gene, involved in autophagy, causes neurodegeneration with brain iron accumulation (NBIA), a disease characterized by global DD in childhood, followed by regression in early adulthood (progressive dystonia, parkinsonism and dementia)." (PMID 34440332, 2021). "WDR45 gene abnormalities are thought to be responsible for other clinical features of BPAN including sudden-onset of progressive dementia and parkinsonism in adolescence." (PMID 34799629, 2021).
developmental delay (8 papers, 2017 to 2026). "A de novo heterozygous frameshift variant in WDR45 was found in a female patient with epileptic encephalopathy, developmental delay, and ASD features." (PMID 40558542, 2025). "We identified a novel c.795delT mutation in the WDR45 gene affecting a girl with a Rett syndrome phenotype who presented with developmental delay with seizures and late regression along with prominent teeth grinding and stereotypical cyclic breathing pattern." (PMID 29075622, 2017). "Variants in WDR45 (WD repeat-containing protein 45; OMIM*300526) are associated with developmental delay in early childhood and progressive neurodegeneration in adolescence or adulthood related to iron accumulation in the globus pallidus and substantia nigra." (PMID 31409060, 2019). "Most notably, in many WDR45 mutation cases, neurological regression does not occur until adolescence, although developmental delays may be prominent early on." (PMID 29075622, 2017).
epilepsy (7 papers, 2021 to 2025). A brain disorder characterized by episodes of abnormally increased neuronal discharge resulting in transient episodes of sensory or motor neurological dysfunction, or psychic dysfunction. "Previously, genes containing the WD repeat domains such as WDR37 and WDR45 have been reported to be associated with epilepsy." (PMID 36514184, 2023). "Currently, a multitude of studies have explored autophagy-related genes, such as WDR45, CYLD, and 4E-BP2, which have been linked with epilepsy development." (PMID 40217519, 2024). "Epilepsy, a feature most common in the first decade of life in BPAN patients, and dystonia, a feature typical of early adulthood, were instead not displayed by Wdr45 KO mice at any age." (PMID 34043061, 2021).
neurodegeneration with brain iron accumulation (7 papers, 2019 to 2025). "Beta-propeller protein-associated neurodegeneration (BPAN) is a subtype of neurodegeneration with brain iron accumulation (NBIA) caused by loss-of-function variants in WDR45." (PMID 36076926, 2022). "De novo mutations in the WDR45/ATG18 gene are associated with a distinct case of Neurodegeneration with Brain Iron Accumulation (NBIA)." (PMID 32269837, 2019). "Recently defined, BPAN is the only X-linked subtype of neurodegeneration with brain iron accumulation (NBIA) due to a de novo mutation in the WD repeat domain 45 (WDR45) gene at the Xp11.23 locus, which is responsible for encoding a beta-propeller scaffold protein, hence the name BPAN." (PMID 37396670, 2023). "De novo heterozygous mutations in WDR45 have been known to cause β-propeller protein-associated neurodegeneration (BPAN), a subtype of neurodegeneration with brain iron accumulation (NBIA)." (PMID 34799629, 2021). "Beta‐propeller protein‐associated neurodegeneration (BPAN, OMIM 300894), a subtype of neurodegeneration with brain iron accumulation (NBIA), is an X‐linked neurodegenerative disorder caused by mutations in WDR45, the gene encoding a member of WIPI family, WDR45 (also called WIPI4)." (PMID 31332960, 2019). "Mutations in the WDR45 (WD repeat domain 45) gene cause beta-propeller protein-associated neurodegeneration (BPAN, OMIM 300894), a subtype of a heterogeneous group of rare, monogenic disorders referred to as neurodegeneration with brain iron accumulation (NBIA)." (PMID 36076926, 2022).
neuroblastoma (6 papers, 2022 to 2025). Neuroblastoma (NB) is the most common solid, extracranial childhood tumor. "These inconsistent observations may be explained by the different cell types used in the studies (fibroblast vs. neuroblastoma cells) or the nature of WDR45 mutations (hypomorphic mutation in the patient cells vs. the null mutations in our study)." (PMID 34837396, 2022). "To elucidate the role of WDR45, we generated a WDR45‐knockout (KO) SH‐SY5Y neuroblastoma cell line using CRISPR‐Cas9‐mediated genome editing." (PMID 34837396, 2022). "Though, neuroblastoma cells lacking WDR45 expression do not have a reduced number of autophagosomes and a recent publication showed autophagy induction does not rescue retinal degeneration in WDR45 deficient zebra fish." (PMID 40092065, 2025). "To assess the role of WDR45 in neuron‐related cells, we inactivated the WDR45 gene in SH‐SY5Y neuroblastoma cells (SH‐SY5YΔWDR45)." (PMID 34837396, 2022).
Dystonia (5 papers, 2013 to 2026). An abnormally increased muscular tone that causes fixed abnormal postures. "Some cases of calcifications have been reported also in BPAN (Beta-Propeller Associated Neurodegeneration, due to mutations in WDR45) in patents with dystonia and neuropsychiatric features." (PMID 36862146, 2023). "New subtypes of neuronal brain iron accumulation have been delineated and linked to mutations in C19orf12 and WDR45, while a new treatable form of dystonia with brain manganese deposition related to mutations in SLC30A10 has been described." (PMID 23757263, 2013).
Intellectual disability (4 papers, 2021 to 2023). "Mutations in WDR45B and WDR45 lead to β-propeller protein-associated neurodegeneration and intellectual disability, respectively." (PMID 36900050, 2023). "Besides BPAN, other phenotypes associated with variants in WDR45 include Rett-like syndrome, intellectual disability, developmental and epileptic encephalopathy and West syndrome." (PMID 36157071, 2022). "Defects in WIPI2 cause a disease characterized mainly by intellectual disability and variable other features while pathogenic variants in WDR45B and WDR45 have been recently reported to cause El-Hattab-Alkuraya syndrome and beta-propeller protein-associated neurodegeneration (BPAN), respectively." (PMID 36157071, 2022). "Among genes with predicted probabilities greater than 0.90 (ranks 1–55), four genes (WDR45, CLTC, BRPF1, and GATAD2B) do not possess SFARI annotations, but have been associated with neurodegeneration and intellectual disability according to OMIM annotations." (PMID 35596027, 2023).
Rett syndrome (3 papers, 2017 to 2023). A severe neurodevelopmental disorder affecting the central nervous system. "This is the first case in which the characteristic breathing pattern of Rett syndrome (periodic hyperventilation followed by apnea) has been reported, thus more tightly associating WDR45 mutations with characteristics of Rett syndrome." (PMID 29075622, 2017). "Whole exome sequencing (WES) revealed a novel c.795delT mutation in the WDR45 gene affecting the girl, which was consistent with her eventual progression to a Rett-like syndrome phenotype including seizures along with a stereotypical cyclic breathing pattern." (PMID 29075622, 2017). "Approximately a dozen cases of patients with WDR45 mutations have been reported to exhibit a Rett-like syndrome presentation." (PMID 29075622, 2017).
Vici syndrome (3 papers, 2016 to 2025). A very rare and severe congenital multisystem disorder characterized by the principal features of agenesis of the corpus callosum, cataracts, oculocutaneous hypopigmentation, cardiomyopathy and combined immunodeficiency. "In the same year as EPG5‐related Vici syndrome, biallelic variants in the WD repeat domain 45 gene (WDR45) were identified in patients with beta‐propeller protein‐associated neurodegeneration with brain iron accumulation." (PMID 39420677, 2025). "At the time of its introduction in 2016, six conditions (EPG5‐related Vici syndrome, WDR45‐related BPAN, SNX14‐related ataxia as well as SPG11‐, ZFYVE26‐, and TECPR2‐related spastic paraplegia) were included with the concept of congenital disorders of autophagy." (PMID 39420677, 2025).
Cognitive impairment (2 papers, 2021 to 2025). Abnormal cognition is characterized by deficits in thinking, reasoning, or remembering. "Together, these data indicate Wdr45 c52C > T mice have impaired performance in learning and memory testing consistent with cognitive impairment seen in BPAN patients." (PMID 40092065, 2025).
depression (2 papers, 2023 to 2024). "Moreover, WDR45cKO mice spent less time in exploration, suggesting that WDR45 dysfunction in midbrain DAergic neurons may lead to depression-like behavior in aging mice." (PMID 39183331, 2024). "Furthermore, the 3-chamber social performance test revealed that the aged WDR45cKO mice displayed a significant decrease in social behavior, suggesting that WDR45 dysfunction in midbrain DAergic neurons may lead to depression-like behavior in aging mice." (PMID 37292937, 2023).
endometrial carcinoma (2 papers, 2019 to 2020). A malignant tumor arising from the epithelium that lines the cavity of the uterine body. "A cross-cancer profiling of ARGs alterations has found that WDR45 was under significantly somatic mutations in endometrial carcinoma, suggesting WDR45 mutation could play a positive role in tumorigenesis." (PMID 33178587, 2020). "Authors found somatic mutations in a number if autophagy genes including RB1CC1/FIP200, WDR45/WIPI4, ULK4, and ATG7 in endometrial carcinoma and clear cell renal carcinoma." (PMID 31850214, 2019).
Neurodegeneration (2 papers, 2017 to 2024). Progressive loss of neural cells and tissue. "Mutations in WDR45 gene, coding for a beta-propeller protein, have been found in patients affected by Neurodegeneration with Brain Iron Accumulation, NBIA5 (also known as BPAN)." (PMID 28261264, 2017).
optic atrophy (2 papers, 2023 to 2026). A disorder characterized by loss of optic nerve fibers. "METHODS: The study group included two brothers aged 26 and 32 years and a 3-year-old girl from another family diagnosed with optic atrophy, all of whom harbored a novel pathogenic variant in WDR45." (PMID 41943080, 2026). "Given the many known associations of optic atrophy with potentially severe neurologic manifestations in syndromes associated with WDR45 and other genes, it is prudent to always refer children to a neurologist for complete evaluation." (PMID 37819743, 2023). "–30 Here the results suggest that variants in the WDR45 gene are linked with X-linked isolated optic atrophy." (PMID 37819743, 2023). "The WDR45 gene has not previously been described to be associated with isolated optic atrophy, but the gene is located (Xp11.23) within the area of the OPA2 locus." (PMID 37819743, 2023). "This variant is novel and the WDR45 gene has not previously been described to be associated with isolated optic atrophy." (PMID 37819743, 2023).
pancreatic cancer (2 papers, 2022 to 2023). "Using univariate Cox regression, a forest map was generated showing seven ARGs associated with pancreatic cancer prognosis: BAK1, ITGA3, BIRC5, WDR45, BAG3, APOL1, and RAB24." (PMID 35488119, 2022).
retinal degeneration (2 papers, 2021 to 2025). Degeneration of the retina. "Ophthalmic examination in mice from the phenotyping cohort (F4 generation) at around 13 months of age showed severe retinal degeneration in 5/13 Wdr45−/− and 5/15 Wdr45 −/Y mice, with clear altered OCT signal depicted in the SD-OCT images as a darker dotted pattern." (PMID 34043061, 2021).
X-linked optic atrophy (2 papers, 2023 to 2026). "CONCLUSIONS: This is the first study to show higher-than-normal iron levels in the tears of patients with X-linked optic atrophy due to a variant in WDR45." (PMID 41943080, 2026). "RESULTS: All three patients with WDR45 X-linked optic atrophy exhibited elevated iron levels in their tears compared to healthy controls." (PMID 41943080, 2026). "We aimed to determine iron levels in tears of patients with WDR45 X-linked optic atrophy compared to healthy controls." (PMID 41943080, 2026). "Regardless, compared to the severe and debilitating manifestations seen with other syndromes associated with WDR45 variants, the phenotype seen here is essentially isolated X-linked optic atrophy." (PMID 37819743, 2023). "Given the results seen here, we suggest that variants in the WDR45 gene are associated with X-linked optic atrophy." (PMID 37819743, 2023). "Taken together, these findings suggest that variants in the WDR45 gene are responsible for isolated X-linked optic atrophy." (PMID 37819743, 2023). "Among two families with isolated X-linked optic atrophy, molecular analysis revealed novel variants in the WDR45 gene in full segregation with the disease." (PMID 37819743, 2023). "Taken together, these findings suggest that certain pathogenic variants in the WDR45 gene are associated with isolated X-linked optic atrophy." (PMID 37819743, 2023).
autism spectrum disorder (1 paper, 2021). A spectrum of developmental disorders that includes autism, and Asperger syndrome. "Features of autism spectrum disorder often present in BPAN children were also documented in Wdr45 KO mice." (PMID 34043061, 2021).
bladder cancer (1 paper, 2021). "When tested as individual gene, 9 genes from the 11-ARG signature (APOL1, ATG4B, CASP3, ITGA3, P4HB, PRKCD, ULK2, and WDR45) exhibited a significant association between mRNA expression levels and overall survival of bladder cancer patients." (PMID 33925460, 2021). "While higher expression of APOL1, ATG4B, ITGA3, WDR45, CASP3, and PRKCD is associated with favorable survival in human bladder cancer patients, increased ULK2 and P4HB mRNA levels are negatively correlated to overall survival of bladder cancer patients." (PMID 33925460, 2021).
brain iron accumulation (1 paper, 2020). "This is a disorder with brain iron accumulation (NBIA) caused by mutations in WDR45, encoding a protein called WIPI4." (PMID 32087199, 2020).
cognitive decline (1 paper, 2021). "Hearing loss, likely confounded by the patients’ marked cognitive decline and therefore reported only in two BPAN cases, was consistently observed in Wdr45 KO mice both from the progression cohort and phenotyping cohort, as revealed by the clickbox and ABR tests." (PMID 34043061, 2021).
cranioectodermal dysplasia (1 paper, 2022). Cranioectodermal dysplasia (CED) is a rare developmental disorder characterized by congenital skeletal and ectodermal defects associated with dysmorphic features, nephronophthisis, hepatic fibrosis and ocular anomalies (mainly retinitis pigmentosa). "Notably, some WD40 repeat proteins were reported to be associated with rare disorders, for example, WDR45 with psychomotor development delay, WDR35 with cranioectodermal dysplasia, and WDR56 with short‐rib thoracic dysplasia, etc.." (PMID 35962600, 2022).